CTTN (cortactin)
Diseases named in the same sentence as CTTN in open-access papers (continued):
Sharing a sentence is not in itself a finding about the gene and the disease.
breast carcinoma (continued). "One of the key findings of our study is the identification of the phosphatase PTP1B as a regulator of cortactin phosphorylation at invadopodia in both rat and human breast carcinoma cells." (PMID 27824079, 2016). "PPFIA1 maps next to CTTN, which encodes for cortactin, and they are co-amplified in 20–30% of HNSCC1, 2 and 10–20% of breast cancer cells." (PMID 27075696, 2016). "In conclusion, the present study showed for the first time that Fe65 can suppress breast cancer cell motility by promoting the acetylation of cortactin by Tip60." (PMID 26166158, 2015). "Clathrin heavy chain and cortactin have been reported to have their expression levels changed in breast cancer." (PMID 25948494, 2015). "It will be interesting to investigate the potential crosstalk between cortactin phosphorylation mediated by Src and the acetylation mediated by Fe65-Tip60 complex in regulating invadopodia formation and breast cancer invasion and metastasis." (PMID 26166158, 2015). "SIRT1 can promote cell migration and metastasis by directly interacting and deacetylating cortactin in breast cancer." (PMID 26318035, 2015). "Overexpression of cortactin has been found in invasive cancers, including glioblastoma, melanoma, breast cancer, and head and neck squamous carcinomas, as a result of the EMS1 gene amplification." (PMID 24465712, 2014). "c-Src tyrosine kinase activity is suppressed by Syk in breast cancer cells and both c-Src and Syk phosphorylate cortactin (CTTN)." (PMID 24523870, 2014). "In breast cancer, the cortactin is over expressed leading to increased cellular motility and invasiveness." (PMID 24808960, 2014). "AFAP1L1 has been reported to be localized to the invadopodia, along with cortactin, in breast cancer cells." (PMID 24723436, 2014). "Cortactin was found to be overexpressed in mammary tumours where its expression correlates with increased tumour invasiveness." (PMID 24808960, 2014). "Blocking of the GEP100-Arf6-AMAP1-cortactin pathway by siRNAs or inhibitors effectively blocks breast cancer invasion and metastasis." (PMID 21858086, 2011). "For example, cofilin expression is frequently increased in glioblastoma and ovarian cancer whereas cortactin is often over-expressed in breast cancer and squamous carcinoma of head and neck." (PMID 21909426, 2011). "Nevertheless, overexpression of cortactin in multiple types of human tumors e.g. in gastric, liver and breast cancer suggests that cortactin is a key regulator of these processes in vivo." (PMID 21886807, 2011). "In this cohort of randomized premenopausal breast cancer patients, we observed that – with high expression of cortactin and low expression of Chk1 – there was a tendency toward an impaired response to tamoxifen." (PMID 18823530, 2008). "By CGH analysis of breast cancer samples, we identified CTTN and FADD as co-amplified with CCND1 at the 11q13 locus, and CHK1 as a marker for the frequently occurring distal 11q deletion." (PMID 18823530, 2008). "The CCND1 and CTTN oncogenes have been putatively proposed as candidate genes for the emergence and maintenance of this amplification event in breast cancer." (PMID 18823530, 2008). "Two genes located within this amplicon, EMS1, encoding cortactin, and CCND1 encoding cyclin D1, were both considered to act as oncogenes in breast cancer, because increased expression of both cortactin and cyclin D1 correlated well with 11q13 amplification." (PMID 16536875, 2006). "Several lines of evidence point to an important role for both cyclin D1 as well as EMS1/cortactin in breast cancer formation." (PMID 16536875, 2006). "Immunohistochemical, Northern and Western blot analyses were performed to study the expression of human transgene cortactin during mammary gland development and in mammary tumors." (PMID 16536875, 2006). "Furthermore, cortactin is phosphorylated by the tyrosine kinases Src and Arg which both localize to invadopodia of breast cancer cell lines, the former being localized to rafts." (PMID 38200575, 2024).
breast carcinoma (continued). "Although previous studies have examined the correlation between cortactin expression and prognosis in patients with breast cancer, the prognostic significance of cortactin expression in breast cancer remains unclear." (PMID 37761244, 2023). "We propose that HER2+ breast cancer patients with high CTTN expression could benefit from combination therapy with trastuzumab and Wnt signaling inhibitors such as FH535." (PMID 36831511, 2023). "In addition to these experimental data, studies revealing a correlation between cortactin expression and prognosis in patients with breast cancer have also been published." (PMID 37761244, 2023). "Unlike the HER2-type breast cancer, cortactin protein expression in TNBC breast cancer is associated with good prognosis based on our data." (PMID 37761244, 2023). "The mechanism implicated in Pyk2-induced invadopodia activity remains to be determine but recent studies have shown that Pyk2 recruits Src kinase into invadopodia and control cortactin phosphorylation in breast cancer cells suggesting a possible mechanism for invadopodia maturation." (PMID 36899008, 2023). "We also investigated whether CTTN had an impact on the response of breast cancer cells to anti-HER2 therapy." (PMID 36831511, 2023). "Because CTTN overexpression is associated with poor disease-free survival of HER2+ breast cancer patients, we assessed the impact of CTTN on CSC activity in HER2+ breast cancer." (PMID 36831511, 2023). "The absence of any association between cortactin expression and the prognosis of patients with breast cancer in these two studies is probably explained by the fact that the molecular subtypes of breast cancer were not separately analyzed in these studies." (PMID 37761244, 2023). "Collectively, we suggest that CTTN could be a potential target for treatment of trastuzumab resistance in HER2 positive breast cancer patients." (PMID 36831511, 2023). "CTTN overexpression is a marker of a poor prognosis in HER2+ breast cancer." (PMID 36831511, 2023). "It is unclear, however, whether CTTN affects tumor initiation and anti-tumor drug resistance in breast cancer." (PMID 36831511, 2023). "We next examined whether Cav2.2 regulated cortactin ubiquitination or deubiquitination in breast cancer cells." (PMID 36137995, 2022). "In addition, we showed that deubiquitinating enzyme USP43 stabilized cortactin and mediated the functions of Cav2.2 in invadopodia formation and metastasis in breast cancer." (PMID 36137995, 2022). "Furthermore, it was recently shown in breast cancer cells that the cortactin-mediated mechanism is promoted by the activation of Pyk2." (PMID 34944779, 2021). "Cortactin is concentrated in invadopodia of head and neck as well as breast cancer cells." (PMID 35008569, 2021). "In turn, CD44 adheres to its ligand and leads to the activation of src and phosphorylation of cortactin, thus, supporting that Nav1.5 may potentiate the invasion of breast cancer cells by the CD44-src-cortactin signaling axis." (PMID 32792949, 2020). "Furthermore, PBF strongly promotes cellular migration and invasion in thyroid and breast cancer cells, and this activity is dependent on the expression of cortactin." (PMID 31637306, 2019). "Furthermore, treatment of mice bearing breast-cancer xenograft with cirmtuzumab inhibited cortactin phosphorylation in vivo and impaired metastatic development." (PMID 31667337, 2019). "We also found that cirmtuzumab could also inhibit Y421 phosphorylation of cortactin in secondary tumors generated from primary breast-cancer PDX cells in vivo." (PMID 31667337, 2019). "Furthermore, we have shown here that overexpression of Arg and cortactin correlates with increased metastasis and poor patient prognosis in breast cancer patients." (PMID 29774130, 2018).
breast carcinoma (continued). "We previously generated stable MDA-MB-231 breast cancer cells with doxycycline (dox)-inducible expression of thoroughly characterized camelid nanobodies targeting CTTN SH3 or NTA domain (CTTN SH3 Nb2 or CTTN NTA Nb212,26, respectively) or FSCN1 (FSCN1 Nb512,29)." (PMID 30353022, 2018). "A large number of evidences indicate that cortactin is overexpressed in various types of human cancers, such as head, neck, and esophageal squamous carcinomas, colorectal carcinoma, gastric cancer, hepatocellular cancer, breast cancer, and ovarian cancers." (PMID 29152154, 2017). "Colocalization of cortactin and a3 is observed in each of the breast cancer cell lines examined." (PMID 27323815, 2016). "mDia1 is essential for binding of MT1-MMP to α-tubulin; thus, in addition to cortactin and actin enriched invadopodia, mDia1 may have functions in breast cancer invasion through mDia1-mediated microtubule regulated signaling." (PMID 26893363, 2016). "Thus, PTP1B regulates cortactin phosphorylation at tyrosine 421 in invadopodium precursors of both rat and human breast carcinoma, limiting invadopodium maturation." (PMID 27824079, 2016). "A few over-expressed genes in cancer are also located in the amplified region of 11q13.3, including MYEOV (myeloma over expressed), ORAOV1 (oral cancer over expressed gene 1), ANO1 in head and neck squamous cell carcinoma, and CTTN in breast cancer and squamous cell carcinomas of the head and neck." (PMID 26386145, 2015). "Unpublished results from our group indicate that the activation of CCR7 in the breast cancer cell line MCF7 leads to the activation of the oncoprotein cortactin and the promotion of cellular structures essential for metastasis like lamellipodia and invadopodia." (PMID 24305507, 2013). "AMAP1 functions by forming a complex with cortactin in invasive breast cancer cells." (PMID 21858086, 2011). "Paxillin and cortactin are relatively abundant proteins in most cultured cells, including both invasive and noninvasive breast cancer cells, and levels of the AMAP1 expression seem to be crucial for formation of this trimeric protein complex at detectable levels." (PMID 19416474, 2009). "In conclusion, at least in our transgenic model cortactin seems not to have a causative role in breast cancer, but appears to be a weak mammary oncogene." (PMID 16536875, 2006). "Cancer development and progression is a multi-step process, therefore, since both cyclin D1 and cortactin are overexpressed in most breast carcinomas with 11q13 amplification, their cooperative action might contribute to breast cancer development." (PMID 16536875, 2006). "Therefore, we investigated the clinicopathological significance of cortactin in breast cancer." (PMID 37761244, 2023). "Moreover, a network interaction map of invadopodia-associated proteins has demonstrated a central role for the EGFR-Pyk-Src-Arg-cortactin invadopodial pathway, in which repurposing of existent inhibitors could be applied for blocking breast cancer metastasis." (PMID 34440806, 2021). "However, treatment of serum-starved breast-cancer PDX cells with exogenous Wnt5a could enhance the level of phosphorylated cortactin within 5 min." (PMID 31667337, 2019). "Nonetheless, we found that cirmtuzumab could inhibit the capacity of Wnt5a to induce tyrosine phosphorylation of cortactin in serum-starved ROR1+breast-cancer PDX, even at Wnt5a concentrations of 100 ng/ml, indicating that the Wnt5a-induced phosphorylation of cortactin was dependent on ROR1." (PMID 31667337, 2019). "ABL kinase inhibitors significantly reduced invadopodium precursor formation as well as cortactin tyrosine phosphorylation and consequent actin polymerization, extracellular matrix degradation, and three-dimensional (3D) tumor cell invasion in invadopodia of inhibitor-treated breast cancer cells." (PMID 29774130, 2018).
breast carcinoma (continued). "In addition, it led to new biological findings concerning molecular paths in breast cancer cells linking the tyrosine kinase Syk and two targets involved in cell adhesion and motility: (i) the signaling axis Syk-Src-cortactin and (ii) the direct action of Syk on ezrin." (PMID 28306714, 2017). "To determine whether MenaINV influenced cortactin phosphorylation at invadopodia we assessed the level of tyrosine 421 cortactin phosphorylation in both human and rat breast carcinoma cells that were serum starved to reduce background levels of cortactin phosphorylation." (PMID 27824079, 2016). "We have shown previously that the GEP100-Arf6-AMAP1-cortactin pathway is used for invasion and metastasis of many breast cancer cells; and in this paper, we show that this pathway is also used in angiogenesis, including breast cancer-induced angiogenesis and choroidal neovascularization." (PMID 21858086, 2011). "In breast cancer, ASAP1 interacts with the SH3 domain of cortactin via its proline‐rich sequence and binds to paxillin via its own SH3 domain, playing a role in promoting invasion." (PMID 40742091, 2025). "This is in line with reduced extravasation when invadopodia components, namely CTTN, LPP and MT1-MMP, are removed from breast cancer cells." (PMID 40419795, 2025). "Invadopodia are F-actin-enriched membrane protrusions regulated by cortactin and specialized in extracellular matrix (ECM) degradation by matrix metalloproteinases (MMP), some of which are known to be upregulated in breast cancer." (PMID 38200575, 2024). "In conclusion, CTTN is a biomarker of a poor prognosis and a possible target for treating the trastuzumab resistance of HER2+ breast cancers." (PMID 36831511, 2023). "To further understand how CTTN affects CSC activity and trastuzumab resistance in HER2+ breast cancer, we performed an RNA-seq analysis of CTTN-overexpressing SKBR3 cells." (PMID 36831511, 2023). "In this study, we have revealed that CTTN not only promotes cancer progression but also plays a crucial role in tumor initiation and anti-cancer drug resistance in HER2+ breast cancer." (PMID 36831511, 2023). "Based on these results, overexpression of cortactin in TNBC and HER2-type breast cancers is presumed to play different roles, or it is judged that different molecular mechanisms are involved." (PMID 37761244, 2023). "Here, we investigated the potential role of CTTN as a novel poor prognostic biomarker and possible therapeutic target of trastuzumab resistance for HER2 positive breast cancer." (PMID 36831511, 2023). "Our findings clarify the role of CTTN in inducing tumor initiation and trastuzumab resistance in HER2+ breast cancer." (PMID 36831511, 2023). "Mechanistically, CTTN downregulates DKK-1, a Wnt antagonist, in HER2+ breast cancer, resulting in activation of the Wnt signaling pathway and expansion of the number of CSCs, as well as resistance to trastuzumab." (PMID 36831511, 2023). "The acetylation of microtubule structures, such as α-Tubulin and cortactin, by α-Tubulin N-acetyltransferase 1 (ATAT1) and TIP60 decreases the formation of invadopodia and inhibits breast cancer cell migration and invasion." (PMID 35216622, 2022). "TKS5, integrin, F-actin, cortactin, and MMP-14 were identified as prognostic markers related to invadopodia and their targeting curbs breast cancer metastasis." (PMID 35008569, 2021). "Inhibition of NRTKs in the PTK2B-Src-ABL2-cortactin cascade, in particular of ABL2, effectively inhibits the invadopodia-mediated invasiveness and metastasis of human breast cancer cells in a mouse tumor model." (PMID 35008569, 2021). "CTTN is over-expressed in many types of cancer, and upregulation of CTTN contributes to the tumorigenesis of many malignancies, including HCC, head and neck squamous cell carcinomas, breast cancer, and esophageal squamous cell carcinoma." (PMID 32120844, 2020).
breast carcinoma (continued). "We established that the proline at 841 of ROR1 was required for it to recruit cortactin and ARHGEF1, activate RhoA, and enhance breast-cancer-cell migration in vitro or development of metastases in vivo." (PMID 31667337, 2019). "We next sought to determine a connection between mRNA expression levels of ABL1, ABL2, and CTTN in breast tumors to overall survival (OS) and disease-free survival (DFS) of breast cancer patients." (PMID 29774130, 2018). "In this study, we have investigated CTTN and FSCN1 function in EV release, using invadopodia-forming MDA-MB-231 breast cancer cells as a model cell line." (PMID 30353022, 2018). "We validate the interaction between ZO-1 and ADAM12 in invasive breast cancer cell lines and show that ZO-1 and ADAM12 co-localize in actin- and cortactin-rich structures." (PMID 29765546, 2018). "In breast cancer cells, ATAT1 binds and regulates cortactin acetylation levels and colocalizes with cortactin at the adherent surface of the cells." (PMID 27322556, 2016). "In fact, the invasiveness of breast cancer cells correlates with the formation of a ternary complex between PKD1, cortactin and paxillin in invadopodia-enriched membranes." (PMID 25287328, 2014). "Recent studies also revealed CD44 overexpression potentiates the migration and invasion of breast cancer cells and promotes metastasis to the liver through CD44–HA / NFκB / cortactin signaling pathway." (PMID 23855374, 2013). "We observed both melanoma and breast cancer cells forming putative invadopodia structures in this assay, which were rich in N-WASP, cortactin, Arp2/3 complex and actin." (PMID 22347388, 2012). "Thus, we have shown that CTTN induces CSC activity, tumor growth, and trastuzumab resistance in HER2+ breast cancer." (PMID 36831511, 2023). "Collectively, these findings demonstrate that CTTN enhances CSC activity and induces trastuzumab resistance, suggesting that CTTN is a possible oncogenic driver and a potential target for overcoming trastuzumab resistance in HER2+ breast cancer." (PMID 36831511, 2023). "Since the amplification of chromosome 11q13 was correlated with lymph node metastasis and increased mortality in patients with breast cancer, they studied the role of two genes located within this amplicon, CCND1 and CTTN, in the development of breast tumors using transgenic mice." (PMID 37761244, 2023). "In this regard, we found that cirmtuzumab could block the capacity of Wnt5a to induce ROR1 to complex and phosphorylate cortactin, recruit ARHGEF1, and activate RhoA, thereby suppressing breast-cancer-cell migration/metastasis." (PMID 31667337, 2019). "Wnt5a also induced ROR1-dependent tyrosine phosphorylation of cortactin (Y421), which recruited ARHGEF1 to activate RhoA and promote breast-cancer-cell migration; such effects could be inhibited by cirmtuzumab, a humanized mAb specific for ROR1." (PMID 31667337, 2019). "Our findings establish a prognostic value for Arg and cortactin as predictors of metastatic dissemination and suggest that therapeutic inhibition of ABL kinases may be used for blocking breast cancer metastasis." (PMID 29774130, 2018). "There was no statistical difference in Cortactin expression between Nischarin positive and negative breast cancer cells." (PMID 29415725, 2018). "Similar results were obtained with an additional human breast cancer cell line named ZR751, which also overexpresses ERBB2, and showed colocalization of cortactin with F-actin and ERBB2 and a peak of CDR formation at 15 min followed by a decrease at 20 min of Tz treatment." (PMID 28947957, 2017). "Up-regulation of the cytoskeletal protein cortactin/EMS1, a relatively specific substrate of c-Src, has been reported to be involved in metastases and correlated with poor outcomes of patients with breast cancer." (PMID 27078847, 2016).